ZBTB7C (zinc finger and BTB domain containing 7C)
Description:
May be a tumor suppressor gene.
Synonyms: APM-1; APM1; ZBTB36; ZNF857C
Tractability: No criterion of Open Targets' tractability assessment is met for any kind of drug.
Gene: Protein-coding gene on chromosome 18 (48,026,672 to 48,410,752, reverse strand). Ensembl gene ENSG00000184828.
Gene Ontology:
Molecular function: DNA-binding transcription factor activity, RNA polymerase II-specific; RNA polymerase II cis-regulatory region sequence-specific DNA binding
Biological process: negative regulation of cell population proliferation; regulation of transcription by RNA polymerase II
Cellular component: nucleus
Genetic constraint (gnomAD): Loss-of-function variants: 8 observed, 22.95 expected, observed/expected ratio (o/e) 0.35, 90% interval 0.2 to 0.63. The upper end of that interval is the gene's LOEUF score, 0.63, which puts it in group 2 of 6, group 1 being the genes least tolerant of losing a copy. Missense variants: 824 observed, 811.58 expected, observed/expected ratio (o/e) 1.02, 90% interval 0.96 to 1.08. Synonymous variants: 394 observed, 345.44 expected, observed/expected ratio (o/e) 1.14, 90% interval 1.05 to 1.24.
Homologues: Orthologues: chimpanzee ZBTB7C (99% identical), macaque ZBTB7C (99% identical), pig ZBTB7C (98% identical), guinea pig ZBTB7C (96% identical), rat Zbtb7c (94% identical), mouse Zbtb7c (94% identical), rabbit ZBTB7C (93% identical), tropical clawed frog zbtb7c (64% identical), zebrafish zbtb7c (53% identical). Paralogues in human: HIC1 (22% identical), HIC2 (17% identical), PRDM1 (14% identical), ZBTB16 (14% identical), ZBTB18 (14% identical), ZNF451 (13% identical), PATZ1 (13% identical), PRDM10 (13% identical), ZNF76 (13% identical), ZBTB42 (12% identical), MTF1 (12% identical), ZNF410 (12% identical), and 24 more.
Diseases named in the same sentence as ZBTB7C in open-access papers:
ZBTB7C is named in the same sentence as 26 diseases in open-access papers, as found by Europe PMC text mining. Sharing a sentence is not in itself a finding about the gene and the disease. The quoted sentences say what the papers report.
cervical cancer (2 papers, 2021 to 2023). A primary or metastatic malignant neoplasm involving the cervix. "Zinc-finger and BTB domain-containing 7B (ZBTB7C), a member of the ZBTB transcription factor family, has reduced or absent expression in most cervical cancer cell lines and has been proven to inhibit the proliferation of cervical cancer cells." (PMID 33946045, 2021).
colorectal cancer (2 papers, 2021). A primary or metastatic malignant neoplasm that affects the colon or rectum. "The ZBTB7C gene has recently been confirmed to be an independent prognostic factor for colorectal cancer (CRC) and a tumor suppressor gene involved in the occurrence and development of colorectal cancer." (PMID 33946045, 2021). "In colorectal cancer (CRC), there was a significant positive correlation between ZBTB7C expression and immune cell infiltration, especially the infiltration of mast cells and B cells." (PMID 33946045, 2021).
bladder cancer (1 paper, 2023). "This strategy identified a large module of Luminal TFs, including known Luminal-associated TFs (e.g., FOXA1/GATA3/PPARG), as well as TFs with yet unexplored roles in Luminal bladder cancer biology (e.g., HES1, FOXQ1, ZBTB7C, MECOM, GRHL2/3, and TBX3)." (PMID 36944729, 2023).
colon adenocarcinoma (1 paper, 2021). "Highly expressed ZBTB7C was beneficial to the survival of patients with colon adenocarcinoma (COAD), lymphoid neoplasm diffuses large B cell lymphoma (DLBC), esophageal carcinoma (ESCA) and mesothelioma (MESO)." (PMID 33946045, 2021).
ischemic stroke (1 paper, 2020). A stroke disorder caused by obstruction of blood flow to the brain, due to thrombotic (local blood clot formation) or embolic (due to a blood clot or other material traveling from another site) event. "ZBTB7C has also been suggested as a susceptibility gene for ischemic stroke through modulation of neuronal apoptosis." (PMID 32193444, 2020).
osteosarcoma (1 paper, 2025). A usually aggressive malignant bone-forming mesenchymal neoplasm, predominantly affecting adolescents and young adults. "Elevated expression of METTL3 incurs an increase in the overall m6A modification level of the oncogene ZBTB7C mRNA, eventually promoting osteosarcoma progression." (PMID 40823087, 2025). "Notably, STM2457 decreases m6A modification levels and weaken ZBTB7C protein abundance, leading to osteosarcoma growth inhibition." (PMID 40823087, 2025). "Furthermore, the increased METTL3 and ZBTB7C levels in human osteosarcoma tissues were confirmed, highlighting their potential as therapeutic targets and STM2457 as a promising drug." (PMID 40823087, 2025).
tumor (5 papers, 2021 to 2024). "Next, we comprehensively explained the important role of ZBTB7C in several tumor types in terms of tumor mutational burden (TMB), microsatellite instability (MSI) and immune cell infiltration." (PMID 33946045, 2021). "The pancancer analysis showed that ZBTB7C expression was significantly low in many tumors, suggesting a tumor suppressor effect." (PMID 33946045, 2021). "The expression patterns and mechanisms of action of ZBTB7C in different tumor cells are significantly different." (PMID 33946045, 2021). "More importantly, ZBTB7C can also regulate tumor glutamine metabolism by affecting the transcription of glutaminase (GLS1)." (PMID 33946045, 2021). "The expression of ZBTB7C showed significant differences according to tumor location." (PMID 33946045, 2021). "In general, the expression level of ZBTB7C in tumor tissues was lower than that in normal tissues." (PMID 33946045, 2021). "Compared with adjacent tissues, most tumor tissues had significantly lower expression of ZBTB7C." (PMID 33946045, 2021). "However, ZBTB7C in clear cell renal cancer cells can function as a proto-oncogene to stimulate the rapid proliferation of tumor cells." (PMID 33946045, 2021). "ZBTB7C, downregulated in CRC, is thought to block Myc and tumor cell glutaminolysis, thus increasing immune cell proliferation due to the glutamine surplus in the tumor microenvironment and attenuating CRC cell proliferation." (PMID 37373394, 2023).
cancer (4 papers, 2021 to 2023). A tumor composed of atypical neoplastic, often pleomorphic cells that invade other tissues. "Recently, we showed that Zbtb7c is vital in gluconeogenesis during fasting and in glutamine metabolism in cancer cells." (PMID 34017061, 2021). "To further evaluate the expression of ZBTB7C across cancers, we used the Oncomine database and the TIMER database to verify and supplement our results." (PMID 33946045, 2021). "In this study, we used R software to process The Cancer Genome Atlas (TCGA) data and explored the expression pattern and prognostic value of ZBTB7C across cancers." (PMID 33946045, 2021). "In conclusion, ZBTB7C can be used as a potential therapeutic target across cancers and is related to immune cell infiltration." (PMID 33946045, 2021). "As a key transcription factor, ZBTB7C has been reported in many different cancers, but current research shows that its expression and function have strong tissue specificity." (PMID 33946045, 2021). "ZBTB7C can be used as a biomarker of prognosis across cancers, and it plays an important role in the recruitment and regulation of infiltrating immune cells in CRC." (PMID 33946045, 2021). "This study found for the first time that ZBTB7C is widely underexpressed and is related to prognosis across cancers; in addition, ZBTB7C is related to TMB, MSI and immune infiltration, especially in COAD." (PMID 33946045, 2021). "The expression of ZBTB7C was significantly correlated with the overall survival (OS) of 4 cancers: COAD (P = 0.006), DLBC (P = 0.001), ESCA (P = 0.031) and MESO (P = 0.001)." (PMID 33946045, 2021). "In summary, we performed a systematic analysis of the expression of ZBTB7C across cancers." (PMID 33946045, 2021). "At both the mRNA level and the protein level, the levels of ZBTB7C, TPSB2, MS4A2, CD19, and MS4A1 in CRC tissues were lower than those in normal tissues adjacent to the cancer." (PMID 33946045, 2021).
infection (1 paper, 2021). The state of being infected such as from the introduction of a foreign agent such as serum, vaccine, antigenic substance or organism. "While ectopic Zbtb7c repressed endogenous Sirt1 expression in NIH3T3 cells, knockdown of Zbtb7c expression by infection with recombinant adenovirus expressing shZbtb7c RNA increased endogenous Sirt1 expression." (PMID 34017061, 2021).
ZBTB7C also shares sentences with these, for which no sentence is quoted: colon cancer (1 paper); epilepsy (1); esophageal carcinoma (1); head and neck squamous cell carcinoma (1); kidney cancer (1); kidney chromophobe (1); lung adenocarcinoma (1); lung squamous cell carcinoma (1); mesothelioma (1); middle cerebral artery infarct (1); Obesity (1); pheochromocytoma and paraganglioma (1); prostate adenocarcinoma (1); rectal adenocarcinoma (1); sarcoma (1); skin cutaneous melanoma (1); thyroid carcinoma (1).